TLR7 (toll like receptor 7)
Diseases named in the same sentence as TLR7 in open-access papers (continued):
Sharing a sentence is not in itself a finding about the gene and the disease.
ovarian carcinoma (7 papers, 2015 to 2023). A malignant neoplasm originating from the surface ovarian epithelium. "The HDACis were used to boost HERV expression in ovarian cancer cells (“shock”), and the TLR7/8 agonists provided the signal for apoptosis of susceptible HERV de-repressed tumor cells (“kill”), inducing a synergistic cytotoxic effect." (PMID 33919186, 2021). "Unresectable/metastatic solid tumours (including ovarian cancer).SHR2150 (TLR7 agonist) and chemotherapy plus anti-PD1 mAb or anti-CD47 mAb (specific mAb identities not provided).Non-randomised, open-label." (PMID 35020853, 2022). "Variable expression of TLR8 was seen in the benign and malignant epithelium of ovarian cancer patients, while expression of TLR7 was weak." (PMID 36476317, 2022). "Although potential therapeutic benefit was reported for a TLR7 agonist used in heavily pre-treated patients, the roles of TLR7 expression in ovarian cancer cells requires further investigation." (PMID 26622942, 2015). "Furthermore, a very recent study showed the enhanced antitumor activity of a novel combination therapy (“shock and kill” strategy) based on HDACis and TLR7/8 agonists in human ovarian cancer cells." (PMID 33919186, 2021). "A diminished capacity of pDCs to produce IFN-α upon TLR7/9 stimulation has been previously reported in HNSCC, breast and ovarian cancers." (PMID 38239354, 2023). "Expression of TLRs in ovarian cancer results showed that advanced-stage patients with TLR7 positivity had a lower OS than patients with negative TLR7 and TLR7 can be an important prognostic marker in ovarian cancer." (PMID 36476317, 2022).
plaque psoriasis (7 papers, 2019 to 2025). "IMO-8400, an antagonist of TLR7/8/9, has been found to reduce moderate-to-severe plaque psoriasis in clinical trial phase IIa patients." (PMID 32660060, 2020). "IMO-8400 inhibits TLR7/TLR8/TLR9 under phase-II clinical trials in patients with moderate to severe plaque psoriasis." (PMID 31582899, 2019). "The oligonucleotide IMO-3100 antagonizes TLR7/TLR9, and IMO-3100 has completed trials in patients with moderate to severe plaque psoriasis (NCT01622348)." (PMID 31582899, 2019). "This future might not be so far away: monospecific TLR7 and TLR9 antagonists are currently under investigation for the treatment of dermatomyositis and plaque psoriasis." (PMID 33168071, 2020).
type 1 diabetes (7 papers, 2020 to 2024). "Endosomal TLR7 is also implicated in the pathogenesis of organ-specific type 1 diabetes (T1D), which leads to insufficient insulin secretion and hyperglycemia." (PMID 36677692, 2023). "Our data suggest that TLR7 contributes to type 1 diabetes development by regulating B-cell functions and subsequent interactions with T cells." (PMID 33432061, 2021). "The expression of the gene encoding toll-like receptor 7 (TLR7) was significantly increased by 70% in individuals with new-onset type 1 diabetes compared with the non-diabetic control group (p = 9.60 × 10−3, 95% CI −0.42, −0.05)." (PMID 33973017, 2021). "TLR7 is a pattern recognition receptor that senses single-stranded RNAs from viruses and host tissue cells; however, its role in type 1 diabetes development remains unclear." (PMID 33432061, 2021). "Identification and avoidance of diabetogenic viruses that can stimulate the toll-like receptor 7 pathway in early disease development may prevent or delay type 1 diabetes." (PMID 33973017, 2021). "Similar to our findings, one study in NOD/ShiLtJ mice that develop SD and type I diabetes (TID) simultaneously found that Tlr7 was not required for salivary gland inflammation in females." (PMID 39310226, 2024). "In our study, we discovered that Tlr7-deficient (Tlr7−/−) nonobese diabetic (NOD) mice, a model of human type 1 diabetes, exhibited a significantly delayed onset and reduced incidence of type 1 diabetes compared with Tlr7-sufficient (Tlr7+/+) NOD mice." (PMID 33432061, 2021). "Moreover, TLR7 was required for type 1 diabetes development in male but not female NOD mice." (PMID 33322152, 2020).
vitiligo (7 papers, 2014 to 2025). Generalized well circumscribed patches of leukoderma that are generally distributed over symmetric body locations and is due to autoimmune destruction of melanocytes. "A genetic association analysis for vitiligo revealed susceptibility loci including TLR7 single nucleotide polymorphisms (SNPs)." (PMID 33371432, 2020). "It is intriguing to note, that topical administration of TLR7 agonist imiquimod has been shown to be associated with vitiligo-like hypopigmentation." (PMID 26442097, 2015). "Three other SNPs from TLR7 region—rs5935436, rs179013, and rs179008—produced weaker allelic associations in entire vitiligo and subgroup analyses." (PMID 26442097, 2015). "The main results were the associations of TLR7 SNPs with vitiligo, while several other associations were obtained from the remaining TLR gene regions." (PMID 26442097, 2015). "Melanocytes collected from vitiligo lesions show an increase of TLR7 and TLR9 expression along with an increase of the apoptosis level and a decrease of the melanin synthetic ability." (PMID 33371432, 2020). "The potential mechanism of imiquimod-induced vitiligo involves interaction with Toll-like receptor 7 (TLR7) present on skin cells, which stimulates the production of various cytokines, including interferon (IFN)-α, tumor necrosis factor alpha (TNF-α), interleukin (IL)-6, IL-1, IL-8, and IL-12." (PMID 40920788, 2025). "Activation of TLR7 may trigger melanocyte apoptosis and thus the appearance of vitiligo symptoms." (PMID 26442097, 2015). "In line with the important role of IFNα in disease pathogenesis, hydroxychoroquine, a TLR7 and TLR9 inhibitor downregulating IFNα production by pDCs, was shown to induce repigmentation of vitiligo lesions in a clinical case reports." (PMID 33936032, 2021). "As described in the section on TLR7, increased expression of TLR7 and TLR9 are observed in melanocytes obtained from vitiligo lesions." (PMID 33371432, 2020). "Interestingly, we showed increased expression of TLR7 and TLR9 in vitiligo melanocytes in a recent study, emphasizing a role of TLR7 and TLR9 in hypopigmentation." (PMID 34614305, 2022). "Additionally, imiquimod binds to Toll-like receptor-7 and −8, increasing production of proinflammatory cytokines such as IFN-α, TNF-α, and LI-12, which play a role in the pathogenesis of vitiligo." (PMID 24928346, 2014).
alcohol abuse (6 papers, 2020 to 2023). The use of alcoholic beverages to excess, either on individual occasions ("binge drinking") or as a regular practice. "While Tlr7 increased selectively in 3xTg-AD mice exposed to alcohol, it increased in the brains of humans with alcohol use disorder and in genes related to antigen presentation, such as H2-K1 and H2-D1, among others." (PMID 37308288, 2023). "TLRs implicated in alcohol abuse such as TLR4 and TLR7 undergo a developmental downregulation across adolescence." (PMID 35559229, 2022). "We have reported that TLR7 might contribute to neurodegeneration with alcohol abuse, with ethanol increasing the expression of TLR7 along with secretion of the endogenous agonist miRNA let-7b in primary ex vivo organotypic brain slice culture (OBSC)." (PMID 33806288, 2021). "Moreover, various proinflammatory cytokines and chemokines derived from TLR4 and TLR7 activation are now recognized as potential markers of psychiatric conditions, including depression, postpartum depression, post-traumatic stress disorders and alcohol use disorders." (PMID 35967446, 2022). "We selected Toll-like Receptor 7/8 (TLR 7/8) because these receptors have been related to TLR4 pathways and alcohol abuse." (PMID 32780740, 2020). "The expression of TLR-7 was significantly low in OPSCC patients with a history of smoking and alcohol abuse." (PMID 33008143, 2020).
Anxiety (6 papers, 2019 to 2024). Intense feelings of nervousness, tension, or panic often arise in response to interpersonal stresses. "TLR7-deficient mice exhibit reduced exploratory behaviors, decreased anxiety, reduced aggression, increased olfaction, and impaired contextual fear memory." (PMID 38891900, 2024). "In contrast, prenatal TLR7 activation in mice with imiquimod induced a phenotype of reduced anxiety-like behavior and fragmented social behavior, including social partners, circadian cues, and gonadal hormone fluctuations, but normal locomotor activity." (PMID 38891900, 2024). "Although Tlr7–/y knockout mice exhibit some behavioral abnormalities in terms of olfaction, anxiety, aggression and contextual fear memory, we cannot be sure if Tlr8 upregulation also influences the phenotype of Tlr7 knockout mice." (PMID 34211474, 2021). "Prenatal TLR7 activation by administration of imiquimod also results in sex-biased differences in anxiety-like behavior, repetitive behavior (self-grooming and marble burying), and disrupted social behavior." (PMID 31684953, 2019). "Prenatal TLR7 activation via administration of the selective agonist imiquimod (5.0 mg/kg) induces a phenotype in offspring characterized by reduced anxiety-like behavior, fragmented social behavior, and altered ultrasonic vocalization patterns at 6–12 weeks of age." (PMID 30610201, 2020). "Furthermore, lack of Tlr7 leads to less anxiety and aggression, better olfaction, and worse contextual fear memory in adult mice." (PMID 31684953, 2019).
co-infection (6 papers, 2018 to 2025). "TLR-7 mRNA was upregulated under co-infection with adapted-H1N1 and hCoV-OC43 in Vero E6 cells with or without any treatments." (PMID 38605110, 2024). "The earlier up-regulatory effect of PEDV/PDCoV co-infection in the expression levels of TLR7, TLR8, and TLR9, as compared with the single-infection groups, support our hypothesis concerning the potential synergistic effect." (PMID 36376395, 2022). "Interestingly, PDCoV/PEDV co-infection showed a transient up-regulatory effect on TLR7, TLR8, and TLR9 by 3 DPI." (PMID 36376395, 2022). "In the caudal fin, Mc+ (1 day after co-infection with T. bryosalomne) fish showed mild immune activation with C4B upregulation, while Tb+ fish exhibited a stronger response involving IFI44, ISG15, RSAD2, and TLR7 signaling." (PMID 40943072, 2025). "RSV has a number of surface proteins that can bind directly with TLR4 and/or TLR7, as well as intracellular receptors such as RIG-I, suggesting that VitD3 may be important in regulating viral or viral-bacterial co-infection." (PMID 32318074, 2020).
cutaneous T-cell lymphoma (6 papers, 2020 to 2025). "R848, the focus of this study, is a TLR7/8 agonist, which is currently approved for topical use to treat skin lesions and cutaneous T cell lymphoma." (PMID 36177449, 2022). "Topical application of imiquimod (TLR7 agonist) or resiquimod (TLR7/8 agonist) has been used successfully to treat several murine tumor models, while resiquimod has also demonstrated efficacy in early-stage cutaneous T-cell lymphoma." (PMID 36319717, 2023). "The TLR7/8 agonist Resiquimod is in clinical studies for treatment of cutaneous T-cell lymphoma." (PMID 32183240, 2020). "Resiquimod, also known as R848, is a small molecule agonist of both TLR7 and TLR8 that has been evaluated using a topical formulation in clinical trials for the treatment of cutaneous T cell lymphoma (CTCL)." (PMID 36123697, 2022).
esophageal squamous cell carcinoma (6 papers, 2020 to 2025). Esophageal squamous cell carcinoma (ESCC) is a type of esophageal carcinoma (EC) that can affect any part of the esophagus, but is usually located in the upper or middle third. "Different TLRs play different roles in different cancers.Increased expression of TLR7 has also been observed in more advanced EC patients and correlated to the grade of differentiation in esophageal SCC." (PMID 36476317, 2022). "lncFMR1-AS1 can bind to TLR7, activate the TLR7/NF-κB signaling, and elevate c-Myc expression, therefore promoting esophageal squamous cell carcinoma (ESCC) proliferation, anti-apoptosis, and invasive capacity." (PMID 35663957, 2022). "Exosomal FMR1-AS1 secreted from esophageal carcinoma CSCs can activate TLR7-NFκB signaling and increase the expression level of c-Myc, which results in esophageal squamous cell carcinoma (ESCC) cell proliferation, anti-apoptosis, and invasion." (PMID 37217932, 2023). "For example, the exosomal FMR1 antisense RNA1, FMR1-AS1, in female esophageal squamous cell carcinoma (ESCC), maintains ESCC and CSC dynamic interconversion, by activating the TLR7/NFκB/c-Myc signaling pathway in ESCC." (PMID 32164712, 2020).
inflammatory bowel disease (6 papers, 2009 to 2025). A spectrum of small and large bowel inflammatory diseases of unknown etiology. "A link to human inflammatory bowel disease (IBD) is the observation that patients carrying mutations in both TLR3 and TLR7 had higher rates of hospitalisation compared with IBD patients without mutations." (PMID 28869283, 2017).
liver disease (6 papers, 2012 to 2021). "Therefore, TLR7 signaling contributes to SLE-associated liver diseases." (PMID 31552019, 2019). "Therefore, we aimed to explore the relationship between these three TLR7 polymorphisms and HBV-related liver diseases in the Chinese Han population to gain a better understanding of the role of TLR7 in the development of HBV infection." (PMID 28963470, 2017). "Subclinical liver disease is common in SLE, thus, in order to determine the effect of HFD and TLR7 expression on liver disease, histopathological evaluation was performed on hematoxylin/eosin and Oil Red O stained liver sections." (PMID 31552019, 2019). "Recently, a possible link between toll-like receptor 7 (TLR7) and liver disease was suggested, although it was limited to fibrosis." (PMID 27279075, 2016). "From these studies, we know that TLR2, TLR7 and TLR9 play key roles in liver diseases and TLR2 has an potential function in the regulation of tumor tolerance, cancer progression and metastasis." (PMID 22815694, 2012). "In contrast, specific TLR7 activation did not exacerbate liver disease in a chronic ethanol-feeding model." (PMID 34884492, 2021). "In this context, we have recently revealed that intracellular TLRs, in particular TLR7, increased at early stages of ALD in humans, whereas TLR4 did not, and was correlated with liver disease severity." (PMID 34884492, 2021).
oral squamous cell carcinoma (6 papers, 2017 to 2026). "The finding that the patients with mild TLR7 expression had slightly better 5-year survival than the patients with strong TLR7 expression was not expected, but a similar result has been reported in patients with oral squamous cell carcinoma." (PMID 31238894, 2019). "We report a single-arm, open-label, pilot clinical trial assessing the efficacy and safety of topical toll-like receptor-7 (TLR-7) agonist, imiquimod, utilized in a neoadjuvant setting in early-stage oral squamous cell carcinoma (OSCC)." (PMID 39931064, 2025).
parasitemia (6 papers, 2018 to 2026). "TLR7 promotes protective humoral immunity during non‐lethal P. yoelii infection by enhancing Tfh differentiation, survival, and B‐cell help via the STAT3/Ikzf2 pathway, whereas TLR7 deficiency impairs antibody responses and increases parasitemia." (PMID 41461395, 2026). "This hypothesis is corroborated by former observations that correlate higher expression of some X-linked genes (Tlr7, Cxcr3, and Tlr8) in females compared to males with better protection against viral or parasite infections in both humans and mice." (PMID 38701219, 2024). "Following P. berghei infection, mice with a deletion in the Fc receptor, FcγRIIB, or transgenic mice overexpressing toll like receptor 7 (TLR-7) had lower levels of cerebral pathology than WT mice, but were unable to control parasitemia." (PMID 30631323, 2018). "Notably, although TLR7/8 agonists have been extensively investigated in antiviral, oncologic, and certain parasitic disease contexts, their integrated role as both immunomodulators and direct antileishmanial agents against L. donovani has remained largely unexplored." (PMID 41115062, 2025). "Wild-type and TLR7-/- mice were infected with P. yoelii NSM and we found that the parasitemia of TLR7-/- infected mice seemed more severe." (PMID 37180169, 2023).
prostate carcinoma (6 papers, 2014 to 2025). A carcinoma that arises from epithelial cells of the prostate gland. "Notably, TLR7 which sense synthetic compounds like Resiquimod (R-848) with potent anti-tumor activity was absent in all prostate cancer cell lines." (PMID 24966802, 2014).
sialadenitis (6 papers, 2020 to 2024). Sialadenitis is an infection of the salivary glands. "Since sialadenitis was increased in both Tlr7-deficient males and females, we sought to analyze the infiltrates in SMG tissue in greater depth." (PMID 39310226, 2024). "Moreover, we demonstrated here that TLR7 signaling is pivotal for the development of associated SS in TLR8ko mice since double TLR7/8ko mice were protected, and that sialadenitis was more profound in female than in male mice." (PMID 34108972, 2021). "In the current study, we found that males and females that lack Tlr7 expression also have increased sialadenitis in salivary tissue and similar salivary production as compared to the parental strain." (PMID 39310226, 2024). "In contrast, Tlr7 expression was primarily protective in male pSD mice, as ablation of Tlr7 in males resulted in elevated sialadenitis and pneumonitis along with increased B and T cell populations as compared to Tlr7-sufficient pSD males." (PMID 39310226, 2024). "Since, exocrine gland inflammation is a hallmark of SS patients, we examined whether 8- and 14-months old TLR8ko female mice with clinical disease of SLE show signs of sialadenitis compared to age- and gender-matched WT and TLR7/8ko mice." (PMID 34108972, 2021). "Since TLR7 and TLR9 are critical in SLE development some studies focused on determining whether TLR7 or TLR9 activation could contribute to sialadenitis in NOD mice." (PMID 36389822, 2022). "In contrast, female NOD mice developed focal sialadenitis regardless of the presence or absence of TLR7, while lacrimal gland inflammation was absent." (PMID 36389822, 2022). "In contrast, females developed focal sialadenitis to a similar degree regardless of the presence or absence of TLR7." (PMID 33322152, 2020). "Hence, we can hypothesize that the accelerated sialadenitis and autoimmune phenotype in the TLR9-deficient MRL/lpr mice is due to the increased TLR7 signaling by B cells, however, this aspect was not addressed in the study." (PMID 36389822, 2022).
Stroke (6 papers, 2017 to 2025). Sudden impairment of blood flow to a part of the brain due to occlusion or rupture of an artery to the brain. "Moreover, there is evidence that stimulation of TLR7 after stroke in adult mice can reduce injury, and is associated with induction of neuroprotective type I IFNs24." (PMID 31267031, 2019). "Although these findings collectively support the potential of targeting TLR7 in mediating brain damage and outcome after stroke regardless sex and aging, further investigation is required in future." (PMID 40191607, 2025). "On the other hand, TLR7 preconditioning [i.e., pre-treatment with a TLR7 agonist, gardiquimod (GDQ), prior to ischemia] has shown protection against subsequent stroke injury through type I IFN-mediated mechanism." (PMID 28769820, 2017). "According to the results, TLR4, TLR7, and TLR8 are all involved in stroke, in which TLR4 and TLR8 have detrimental roles in ischemic stroke, while the activation of TLR7 can induce robust neuroprotection against stroke by triggering a novel type I interferon-mediated mechanism." (PMID 32565722, 2020).